ENSG00000212421
Synonyms: LOC124900285
Gene: Small nucleolar RNA gene on chromosome 9 (87,260,450 to 87,260,585, forward strand). Ensembl gene ENSG00000212421.
Gene Ontology:
Biological process: RNA processing
Cellular component: nucleolus
Homologues: Orthologues: rat LOC120095457 (71% identical), rat LOC120094012 (66% identical). Paralogues in human: SNORA26 (78% identical).